TSSC4 (tumor suppressing subtransferable candidate 4)
Description:
Protein associated with the U5 snRNP, during its maturation and its post-splicing recycling and which is required for spliceosomal tri-snRNP complex assembly in the nucleus. Has a molecular sequestering activity and transiently hinders SNRNP200 binding sites for constitutive splicing factors that intervene later during the assembly of the spliceosome and splicing. Together with its molecular sequestering activity, may also function as a molecular adapter and placeholder, coordinating the assembly of the U5 snRNP and its association with the U4/U6 di-snRNP.
Tractability: Small molecule: a structure with a bound ligand is known. PROTAC: ubiquitination databases record sites on it; its protein half-life has been measured.
Gene: Protein-coding gene on chromosome 11 (2,400,488 to 2,403,878, forward strand). Ensembl gene ENSG00000184281.
Subcellular location: Nucleus; Cytoplasm
Subcellular location (Human Protein Atlas): Nucleoplasm; Cytosol
Gene Ontology:
Molecular function: molecular sequestering activity; protein binding; protein-containing complex binding
Biological process: spliceosomal snRNP assembly; spliceosomal tri-snRNP complex assembly
Cellular component: cytoplasm; nucleus; U5 snRNP
Genetic constraint (gnomAD): Loss-of-function variants: 2 observed, 1.52 expected, observed/expected ratio (o/e) 1.32, 90% interval 0.43 to 1.91. That is too few expected variants to judge how well the gene tolerates losing a copy. Missense variants: 483 observed, 409.88 expected, observed/expected ratio (o/e) 1.18, 90% interval 1.09 to 1.27. Synonymous variants: 247 observed, 185.26 expected, observed/expected ratio (o/e) 1.33, 90% interval 1.2 to 1.48.
Homologues: Orthologues: macaque TSSC4 (97% identical), chimpanzee TSSC4 (80% identical), dog TSSC4 (68% identical), rat Tssc4 (62% identical), mouse Tssc4 (61% identical), pig TSSC4 (57% identical), zebrafish tssc4 (26% identical), tropical clawed frog tssc4 (24% identical), Drosophila melanogaster CG6674 (14% identical).
Diseases named in the same sentence as TSSC4 in open-access papers:
TSSC4 is named in the same sentence as 3 diseases in open-access papers, as found by Europe PMC text mining. Sharing a sentence is not in itself a finding about the gene and the disease. The quoted sentences say what the papers report.
glioblastoma multiforme (1 paper, 2024). "Depletion of TSSC4 in EGFRvIII-expressing glioblastoma multiforme (GBM) cells shifted the function of autophagy from a pro-cell survival role to a pro-cell death role during prolonged cell growth." (PMID 39697342, 2024). "TSSC4 knockdown has been shown to increase cell proliferation in the breast cancer cell line MDA-MB-231, the glioblastoma multiforme (GBM) cell lines U87 and U373, and the cervical cancer cell line HeLa." (PMID 39697342, 2024).
tumor (3 papers, 2013 to 2024). "In our study, we investigated the role of TSSC4, a component of the U5 small nuclear ribonucleoprotein (snRNP), which promotes tri-snRNP formation and acts as a novel tumor suppressor by inhibiting cell proliferation and tumor growth." (PMID 39697342, 2024). "Collectively, these results demonstrate that TSSC4 deficiency leads to aberrant alternative splicing and increased expression of oncogenes, further supporting the role of TSSC4 as a tumor suppressor." (PMID 39697342, 2024). "Previous studies have shown that TSSC4 functions as a tumor suppressor, inhibiting cancer cell and tumor growth." (PMID 39697342, 2024). "Tumor suppressing subtransferable candidate 4 (TSSC4) is a known tumor suppressor and has been identified as part of the U5 small nuclear ribonucleoprotein (snRNP), which is involved in tri-snRNP biogenesis." (PMID 39697342, 2024). "It has been reported that TSSC4 inhibits cancer cell and tumor growth and prevents cell death during excessive growth by inhibiting autophagy." (PMID 39697342, 2024). "We also found six tumor related genes, TUSC2, TP53I3, TSSC4, RAB23, RAB39A, and ERG, which function as either tumor suppressor genes or oncogenes." (PMID 24007313, 2013).
cancer (2 papers, 2022 to 2024). A tumor composed of atypical neoplastic, often pleomorphic cells that invade other tissues. "TSSC4 expression is associated with Beckwith-Wiedemann syndrome and different types of cancers including Wilms tumor, rhabdoid tumors, rhabdomyosarcoma, and lung, ovarian and breast cancers." (PMID 35309946, 2022). "In the future, we will verify TMZ-induced AuICD in more types of GBM cells and investigate the roles of TSSC4 in cell death in different types of cancer cells with diverse genetic backgrounds." (PMID 35309946, 2022).